MTNR1A (melatonin receptor 1A)
Diseases named in the same sentence as MTNR1A in open-access papers (continued):
Sharing a sentence is not in itself a finding about the gene and the disease.
Alzheimer disease (3 papers, 2012 to 2026). A progressive, neurodegenerative disease characterized by loss of function and death of nerve cells in several areas of the brain leading to loss of cognitive function such as memory and language. "piR_015520, located in intron 1 of the human Melatonin receptor 1A (MTNR1A) gene, was detected in the brain where deregulation of the MTNR1A occurred in neurodegenerative diseases such as Alzheimer’s disease." (PMID 22493715, 2012).
diabetes (3 papers, 2023 to 2025). "Considering that oxidative stress, inflammation, and sympathetic activation participate in the etiopathogenesis of DKD, it is plausible that variants in the gene encoding MTNR1A modulate the susceptibility to renal function decline in the context of diabetes mellitus." (PMID 38549765, 2024). "Among the studied melatonin receptor genes, MTNR1B MTNR1A, and RORA showed strong association with both diabetes and obesity." (PMID 40697662, 2025). "For MTNR1A, the receptor for melatonin, diabetes reduces its expression, and its ligand melatonin is associated with platelet activation and function." (PMID 37264453, 2023). "However, MTNR1A and RORA are not included in the main disease cluster studied, showing that MTNR1B, among melatonin receptors, has a stronger association to metabolic diseases such as obesity and diabetes." (PMID 40697662, 2025).
androgen excess (2 papers, 2022 to 2025). "Furthermore, to decipher the association between MTNR1A and hyperandrogenism, we made use of the human granular cell-like KGN cell line for mechanism investigation." (PMID 36353509, 2022). "Overall, our finding demonstrates the significant influence of circadian rhythms on PCOS occurrence, suggests that MTNR1A and AR play vital roles in pathological progression of hyperandrogenism, and broadens current treatment strategies for PCOS in clinical practice." (PMID 36353509, 2022). "To study the role of Mtnr1a in hyperandrogenism of PCOS and investigate whether the pathological changes could be reversed, we applied two different rescue treatment methods following darkness intervention." (PMID 36353509, 2022). "It suggested that AR-overexpression could block out the effect of MTNR1A, and AR acted as an important downstream factor of MTNR1A in aromatase production, thus playing a vital role in the PCOS-related pathophysiological process of androgen excess." (PMID 36353509, 2022).
autism spectrum disorder (2 papers, 2010). A spectrum of developmental disorders that includes autism, and Asperger syndrome. "MTNR1A and MTNR1B variants identified in 295 patients with autism spectrum disorder, 362 controls, and 284 individuals from the human genome diversity panel." (PMID 20657642, 2010).
Calcium nephrolithiasis (2 papers, 2011 to 2020). The presence of calcium-containing calculi (stones) in the kidneys. "This was the first genetic polymorphism investigation to link the MTNR1A–biological melatonin system to calcium nephrolithiasis." (PMID 32685724, 2020). "In a recent study, we identified a genetic link between variants of intron 1 of the melatonin receptor 1A (MTNR1A) gene and calcium nephrolithiasis." (PMID 21818375, 2011).
idiopathic osteoporosis (2 papers, 2025 to 2026). "Recently, mutations in the melatonin receptor 1A (MTNR1A) have been identified as a genetic cause of idiopathic osteoporosis (IOP), providing further evidence for the repurposing of melatonin as a potential therapy for OP." (PMID 40153577, 2025). "Furthermore, we investigate the role of MTNR1A genetic variants in idiopathic osteoporosis and the association between decreased MTNR1A expression and membranous nephropathy." (PMID 42139078, 2026).
kidney stone (2 papers, 2020 to 2021). "Their study confirms that the MTNR1A gene is expressed in the kidney and supports the idea that the biological melatonin system may be involved in renal physiology and the pathogenesis of nephrolithiasis." (PMID 32685724, 2020).
melanoma (2 papers, 2016 to 2023). A malignant, usually aggressive tumor composed of atypical, neoplastic melanocytes. "To determine whether levels of MTNR1A or MTNR1B expression might be associated with disease outcome in melanoma patients, we examined publicly available expression data from TCGA." (PMID 37834395, 2023). "Following UVB exposure, MTNR1A expression has been shown to be upregulated in normal neonatal epidermal melanocytes and downregulated in melanoma lines." (PMID 27023475, 2016).
membranous nephropathy (2 papers, 2021 to 2026). "hnRNPL impacts the pathological conditions of membranous nephropathy by stabilizing the MTNR1A transcript." (PMID 33461173, 2021).
acne (1 paper, 2025). An inflammatory process of the sebaceous glands which is characterized by comedones, nodules, papules and/or pustules on the skin. "The multivariate model revealed that the rs2119882 variant of the MTNR1A gene in homozygosis (CC) was most strongly associated with acne risk (OR = 3.97, 95% CI: 1.01–15.69; p = 0.049)." (PMID 40705802, 2025). "Subgroup analysis among night shift workers revealed a significant association between MTNR1A rs2119882 and acne risk, such that carriers of the CC genotype exhibited increased susceptibility (adjusted OR = 3.97, p = 0.049)." (PMID 40705802, 2025). "Binary logistic regression was used to explore the associations of different genetic models of MTNR1A rs2119882 and CLOCK rs1801260 with acne susceptibility." (PMID 40705802, 2025). "This study aims to explore the relationship between MTNR1A rs2119882 and CLOCK rs1801260 variants and acne risk in Chinese occupational populations, with a focus on shift-working gas station employees." (PMID 40705802, 2025). "Given the overlap, it is biologically plausible that dysfunction of MTNR1A under circadian disruption contributes to acne pathogenesis." (PMID 40705802, 2025). "This study aimed to explore the relationship between circadian rhythm gene polymorphisms, specifically MTNR1A rs2119882 and CLOCK rs1801260, and the risk of acne in an occupational population." (PMID 40705802, 2025). "Association between MTNR1A and CLOCK genes polymorphisms and acne risk among night shift workers." (PMID 40705802, 2025). "However, when analyzing the distribution of acne cases across different genotypes of the MTNR1A rs2119882 and CLOCK rs1801260 polymorphisms, individuals with the GG genotype exhibited a significantly higher acne prevalence (75%) compared to those with the AA genotype (27.4%) (p = 0.034)." (PMID 40705802, 2025). "Polymorphisms in circadian genes, such as MTNR1A rs2119882 and CLOCK s1801260, may amplify the physiological effects of circadian misalignment, leading to increased sebum production, follicular inflammation, and oxidative stress—all hallmarks of acne development." (PMID 40705802, 2025).
amyotrophic lateral sclerosis (1 paper, 2024). Amyotrophic lateral sclerosis (ALS) is a neurodegenerative disease characterized by progressive muscular paralysis reflecting degeneration of motor neurons in the primary motor cortex, corticospinal tracts, brainstem and spinal cord. "Interestingly, melatonin itself is involved in regulating the expression of MTNR1A and has been found to play a role in mitigating anti-infection and anti-oxidative stress damage by inhibiting the loss of MTNR1A in amyotrophic lateral sclerosis." (PMID 38440074, 2024).
Arthritis (1 paper, 2019). Inflammation of a joint. "Case-only analysis indicated that AA genotype frequency in rs2165667 (MTNR1a) AA genotype and rs1562444 (MTNR1b) A/G allele frequency were at increased risk for arthritis and rs10830962 (MTNR1b) CC/CG genotype was at decreased risk for malar rash." (PMID 31815152, 2019). "In MTNR1a/b genes, a significantly increased AA genotype frequency of rs2165667 (MTNR1a) and A allele frequency of rs1562444 (MTNR1b) were found in patients with arthritis than those without (both P = 0.024)." (PMID 31815152, 2019).
autistic disorder (1 paper, 2010). "The promoter variant in MTNR1A was identified in a patient with PDD-NOS and the two MTNR1B mutations were identified in one patient with PDD-NOS (c.-39GC>AA) and one patient with autistic disorder (V124I)." (PMID 20377855, 2010).
autoimmune disease (1 paper, 2020). A disorder resulting from loss of function or tissue destruction of an organ or multiple organs, arising from humoral or cellular immune responses of the individual to their own tissue constituents. "Melatonin receptors MTNR1A and MTNR1B SNPs have been linked to autoimmune diseases, including Graves' disease in a study on 83 Hashimoto's thyroiditis showing variations of rs2119882 of MTNR1A supporting melatonin pathway involvement in Graves' disease pathogenesis." (PMID 32685724, 2020).
autoimmune thyroid disease (1 paper, 2017). Inflammatory disease of the thyroid gland due to autoimmune responses leading to lymphocytic infiltration of the gland. "Possible associations of single-nucleotide polymorphisms (SNPs) of melatonin receptor type 1A (MTNR1A) and 1B (MTNR1B), with autoimmune thyroid disease in an ethnic Chinese (i.e., Taiwanese) population were examined." (PMID 28961261, 2017).
brain injuries (1 paper, 2023). "Similar to the present study, it has been reported that the Mtnr1a gene and protein deficiencies in hypoxic-ischemic mice with brain injuries were reduced by applying melatonin in vivo." (PMID 37605723, 2023).
cancer of the prostate (1 paper, 2021). "Despite the important associations between the pineal hormone, MT1 receptor and prostate cancer, studies investigating the MTNR1A genetic polymorphisms in regard to the prostatic diseases are lacking." (PMID 35008896, 2021).
glioblastoma (1 paper, 2026). The most malignant astrocytic tumor (WHO grade IV). "In this study, transcriptomic data from TCGA, CGGA, and GTEx were integrated to characterize the expression patterns of melatonin receptors (MTNR1A and MTNR1B) and biosynthetic enzymes (AANAT and ASMT) across normal brain tissue, lower-grade glioma and glioblastoma." (PMID 42286740, 2026).
glioma (1 paper, 2026). A benign or malignant brain and spinal cord tumor that arises from glial cells (astrocytes, oligodendrocytes, ependymal cells). "Immunohistochemistry confirmed reduced MTNR1A and ASMT protein expression in glioma tissues." (PMID 42286740, 2026).
Glucose intolerance (1 paper, 2022). Glucose intolerance (GI) can be defined as dysglycemia that comprises both prediabetes and diabetes. "Together, this finding reveals that long-term circadian rhythm misalignment could result in PCOS-like hormonal and reproductive disorder, along with glucose intolerance, and MTNR1A acts as an important connecting factor between circadian rhythm dysfunction and PCOS pathophysiology." (PMID 36353509, 2022).
Hearing impairment (1 paper, 2021). A decreased magnitude of the sensory perception of sound. "To date, F11, MTNR1A, and ZFP42 have not been associated with hearing impairment or inner ear anomalies." (PMID 33418956, 2021).
hepatocellular carcinoma (1 paper, 2021). A malignant tumor that arises from hepatocytes. "In a large Taiwan study, five MTNR1A SNPs (rs13140012, rs6553010, rs2119882, rs13113549, and rs2375801) as well as five MTNR1B SNPs (rs1387153, rs1562444, rs4611171, rs10765576, and rs10830963) were evaluated in patients with hepatocellular carcinoma cancer (HCC)." (PMID 35008896, 2021).
Hyperinsulinemia (1 paper, 2020). An increased concentration of insulin in the blood. "Because these patients have hyperinsulinemia and IR, genes like MTNR1A/B related to insulin secretion possibly play a crucial role in PCOS progression." (PMID 32463080, 2020).
idiopathic scoliosis (1 paper, 2019). A scoliosis with no known cause. "Diseases that are related to MTNR1A include idiopathic scoliosis and scoliosis." (PMID 31581572, 2019).
lung carcinoma (1 paper, 2019). "Lung cancer cell lines that represent different histology subtypes showed a higher expression level of MTNR1A mRNA (p = 0.0058) in NCI-H1703 (SCC) cell line compared to A549 (AC) (* p < 0.05)." (PMID 31319607, 2019).
medulloblastoma (1 paper, 2013). A malignant, invasive embryonal neoplasm arising from the cerebellum. "MTNR1A, a GPCR for melatonin, is significantly under-expressed only in the Non-WNT/SHH group of medulloblastoma tumors (0.0065-fold, p = 0.02)." (PMID 24252460, 2013).
myocardial ischemia (1 paper, 2020). A disorder of cardiac function caused by insufficient blood flow to the muscle tissue of the heart. "In rat both MTNR1A (MT1) and MTNR1B (MT2) are expressed in myocardium, and MTNR1B was upregulated after myocardial ischemia/reperfusion in mice." (PMID 33071966, 2020).
retinal degeneration (1 paper, 2020). Degeneration of the retina. "Phenotype analysis revealed no obvious retinal degeneration in F2 mtnr1a VIL homozygotes." (PMID 32792587, 2020).
schizophrenia (1 paper, 2022). A major psychotic disorder characterized by abnormalities in the perception or expression of reality. "Genetic studies have revealed that variants in the promoter region of the melatonin receptor gene, MTNR1A, may be associated with schizophrenia and sleep disorders." (PMID 35225953, 2022).
Stroke (1 paper, 2024). Sudden impairment of blood flow to a part of the brain due to occlusion or rupture of an artery to the brain. "There was no statistical significance between stroke characteristics and telomere length, NR3C1, TNF-α, BDNF, MTNR1A, or MTNR1B expression." (PMID 38802847, 2024).
type 1 diabetes (1 paper, 2024). "Considering that melatonin is a powerful antioxidant compound, our aim was to explore, in a longitudinal cohort study of type 1 diabetes (T1D) individuals, the association of microvascular complications and SNPs in the gene encoding melatonin receptor 1A (MTNR1A)." (PMID 38549765, 2024).
uveal melanoma (1 paper, 2024). A melanoma derived from melanocytes of the uveal tract. "This, to the knowledge of the authors, is the first investigation of MTNR1A in human uveal melanoma tissue." (PMID 39201396, 2024). "We examined the expression of melatonin receptors in uveal melanoma tumors from two separate cohorts and identified the presence of four receptors including the two main melatonin receptors MTNR1A and MTNR1B as well as RORα and NQO2." (PMID 39201396, 2024). "In the study, receptor agonists for both MTNR1A and MTNR1B as well as melatonin itself inhibited the growth of uveal melanoma cells at physiological concentrations, thereby suggesting a receptor-mediated mechanism for the inhibition of tumor cell growth." (PMID 39201396, 2024). "As previously stated, an earlier study found that MTNR1A and MTNR1B agonists as well as melatonin had a beneficial effect on uveal melanoma cells." (PMID 39201396, 2024). "There was also a higher MTNR1A OD in the cytoplasm of those who died from uveal melanoma compared to those who did not (Holm-Bonferroni corrected p = 0.004)." (PMID 39201396, 2024).
cancer (15 papers, 2013 to 2026). A tumor composed of atypical neoplastic, often pleomorphic cells that invade other tissues. "The MTNR1A rs7665392 T>G minor allele is protective for postmenopausal women but increases the cancer risk in premenopausal women." (PMID 35008896, 2021). "Mounting evidence indicates that melatonin exhibits oncostatic properties in many cancer types mainly mediated by its membrane-bound receptors, melatonin receptor 1A (encoded by MTNR1A) and 1B (MTNR1B)." (PMID 29163852, 2017). "Increasing evidence indicates that melatonin exhibits oncostatic properties in many cancer types at least in part mediated by its membrane-bound receptors, melatonin receptor 1A (encoded by MTNR1A) and 1B (MTNR1B)." (PMID 29156748, 2017). "One previous study reported that the alteration of DNA methylation in the putative promoter region of the MTNR1A gene may induce pathways that increase cancer risk for nightshift workers." (PMID 37370427, 2023). "Other studies investigating immunohistochemically stained tissues from other cancer types have found similar results with higher levels of MTNR1A in the tumors of patients with more advanced stages and worse prognosis." (PMID 39201396, 2024). "Among them, six melatonergic genes were significant unfavorable factors in cancers (e.g., MTNR1A in ESCA and LIHC; GPR50 in KIRC, LIHC, and STAD; NQO2 in BRCA, LIHC, and LUSC; CYP1B1 in KIRC and STAD; ASMT in ESCA, HNSC, and LUAD; and MTNR1B in STAD)." (PMID 33842355, 2021). "The mRNA levels of VEGF, NFkB, MMP2, MMP9, CDKN2a-p16 and MTNR1a were considerably higher in the carcinomas from PNT rats." (PMID 32499868, 2020). "Increased expressions of MTNR1A and MTNR1B have been shown to promote the inhibitory actions of melatonin on the growth of cancer cells." (PMID 29163852, 2017). "MTNR1A is vastly more abundant than MTNR1B, and there is evidence that melatonin’s growth-inhibitory effects on several cancer cells are MTNR1A receptor-dependent." (PMID 25806809, 2015).
tumor (11 papers, 2012 to 2026). "A significant association between MTNR1A polymorphisms and oral carcinogenesis has been demonstrated, and MTNR1A has been designated a putative tumor suppressor." (PMID 27023475, 2016). "All three have been identified as potentially important players in mediating breast cancer risk, but only MTNR1A was reportedly correlated with tumor sizes and survival rates in patients with OSCC." (PMID 25806809, 2015). "Expression of AANAT, ASMT, MTNR1A and MTNR1B progressively declined with increasing tumour grade and was associated with poor prognosis." (PMID 42286740, 2026). "In mammals, MT typically regulates survival signaling and tumor progression through two G protein-coupled membrane receptors, namely MT receptor 1 A (MTNR1A) and MT receptor 1B (MTNR1B)." (PMID 41145438, 2025). "Silencing of MTNR1a gene in OSCC specimens has been correlated to tumor size and shorter overall survival." (PMID 32499868, 2020). "In the current study, mRNA expression for MTNR1a and MTNR1b genes was detected in the tumor microenvironment." (PMID 32499868, 2020). "Moreover, while MT typically regulates survival signaling and tumor progression through its G protein-coupled membrane receptors, MTNR1A and MTNR1B, our findings suggest a receptor-specific effect." (PMID 41145438, 2025). "No tumors expressed GPR50 in this study, however, considering the potential role of MTNR1A in tumor suppression based on previous research, future studies investigating GPR50 may be of value." (PMID 39201396, 2024). "Higher MTNR1A RNA levels were observed in patients with a BRCA1 Associated Protein 1 (BAP1) mutation, and higher NQO2 RNA levels were noted in patients with the epithelioid tumor cell type." (PMID 39201396, 2024). "In the search for switched-off suppressors, the detailed examination of OSCC lines for bi-allelic deleted regions found a common ~1 Mb genetic loss at 4q35 where the melatonin receptor 1A gene is mapped, thus suggesting MT1 as a new candidate for tumor suppressor in OSCC." (PMID 31684096, 2019). "Together with the known tumor-suppressive functions of melatonin and the presence of MTNR1A in various tumors, the MTNR1A is likely target for epigenetic silencing at loci 4q35 and may play a pivotal role during oral carcinogenesis." (PMID 22792106, 2012).
metabolic disease (1 paper, 2025). A congenital disorder (due to inherited enzyme abnormality) or acquired (due to failure of a metabolically important organ) disorder resulting from an abnormal metabolic process. "Notable, MTNR1B gene showed a more prominent association with clusters related to metabolic diseases, including glucose metabolism, compared to related genes such as MTNR1A or RORA." (PMID 40697662, 2025).
renal diseases (1 paper, 2020). "Further studies on larger patient groups should be conducted on melatonin membrane receptor 1A (MTNR1A) SNP (rs13140012) in renal diseases." (PMID 32685724, 2020).